ALKBH1 (alkB homolog 1, histone H2A dioxygenase)
Diseases named in the same sentence as ALKBH1 in open-access papers (continued):
Sharing a sentence is not in itself a finding about the gene and the disease.
tumor (29 papers, 2012 to 2025). "In gastric cancer, ALKBH1 expression has been associated with tumor-associated macrophages, influencing tumor progression and immune evasion, making it a potential target for enhancing anti-tumor immunity." (PMID 39861138, 2025). "We aimed to investigate the potential association between ALKBH1 expression and the tumor microenvironment of STAD, particularly in macrophages." (PMID 38317214, 2024). "Targeting ALKBH1 inhibits tumor growth and reduces stemness and tumorigenesis by down-regulating expression of hypoxia-associated genes and other tumor-associated genes." (PMID 32296573, 2020). "Functionally, the ALKBH1-reduced m6A level regulating a hypoxia-response gene signature is associated with tumor grade and reduced patient survival and functions as a therapeutically targetable node." (PMID 31797919, 2019). "Our findings suggest that the ALKBH1 cluster network is involved in inflammatory and immune-related pathways and may serve as a new diagnostic window for monitoring the tumor microenvironment." (PMID 38317214, 2024). "Depletion of ALKBH1 could cause transcriptional silencing of oncogenic pathways through decreasing chromatin accessibility and inhibit tumor cell proliferation." (PMID 35371987, 2022). "ALKBH1 overexpression accelerated tumor growth by analyzing of excised tumor photos, 28-day tumor growth curves (P < 0.001), and tumor weights (P < 0.001)." (PMID 40867005, 2025). "Given the significant role of ALKBH1 in tumor development, the development of ALKBH1 inhibitors has garnered attention." (PMID 40867005, 2025). "ECM stiffness-induced ALKBH1 upregulation selectively targets tumor-suppressive genes, driving CRC progression." (PMID 40867005, 2025). "The immunohistochemical results indicated that the expression of ALKBH1 was significantly decreased in the in orthotopic xenograft tumor tissues of the shALKBH1 group, and the corresponding degree of DNA 6 mA modification increased." (PMID 40867005, 2025). "We conducted differential gene expression, protein correlation, pathway, and prognostic analyses to examine the clinical significance of ALKBH1 in different tumor types and stages." (PMID 38317214, 2024). "We also determined the association between ALKBH1 expression and TIME at the single-cell and whole-tissue levels, and identified a possible mechanism accounting for its tumor-promoting role." (PMID 38317214, 2024). "We validated the clinical significance of ALKBH1 by analyzing immunohistochemical staining data from the Human Protein Atlas, which confirmed that ALKBH1 protein was upregulated in STAD tumor tissues compared to normal tissues." (PMID 38317214, 2024). "Suppression of ALKBH1 led to heightened N6mA levels in genomic DNA, promoting tumor colony formation and cell migration." (PMID 38317214, 2024). "This study seeks to explore the clinical and pathological relevance of ALKBH1, its impact on the tumor immune microenvironment, and its potential for precision oncology in STAD." (PMID 38317214, 2024). "Elevated ALKBH1 expression is associated with unfavorable outcomes in STAD, impacting both the tumor microenvironment and macrophage infiltration." (PMID 38317214, 2024). "We further examined the genetic alterations of ALKBH1 in different tumor types in the TCGA dataset and observed that STAD tumors had the fourth highest frequency of genetic alterations, mainly mutations, Amplification, and Deep deletion." (PMID 38317214, 2024). "This study highlights that Copy Number Variations (CNV) and mutation status associated with the ALKBH1 gene regulate the progression of STAD, concurrently influencing immune cell infiltration in the tumor microenvironment." (PMID 38317214, 2024). "Since macrophages exhibit tissue-resident properties and possess pro- or anti-inflammatory functions, we further analyzed the relationship between ALKBH1 and tumor immune interactions." (PMID 38317214, 2024).
tumor (continued). "We underscore the significance of ALKBH1 within the tumor immune microenvironment, suggesting its utility as a precision medicine tool and for drug screening in the management of STAD." (PMID 38317214, 2024). "Surprisingly, silencing ALKBH1 increases N6mA levels in genomic DNA, ultimately amplifying tumor colony formation and cell migration." (PMID 38317214, 2024). "Our results indicate that ALKBH1 is significantly overexpressed in late stage, highly metastatic status, and highly malignant tumor grades." (PMID 38317214, 2024). "Knockdown of ALKBH1 resulted in increased levels of N6mA in genomic DNA, which conversely enhanced tumor colony formation and cell migration." (PMID 37007161, 2023). "The staining intensity of TRMT61B, TRMT10C and ALKBH1 in tumor tissue is higher than that in normal kidney tissue." (PMID 37542141, 2023). "The results presented that the genetic alteration rates of ALKBH1-8/FTO in GBM tumor samples were 2.9%, 1.9%, 1.7%, 10%, 1.5%, 2.4%, 2.2%, 1% and 3%, respectively." (PMID 35371987, 2022). "From the results, it is clear that the mRNA expression level of ALKBH1/2/4/6 was positively correlated with tumor stage." (PMID 34150745, 2021). "Furthermore, there is a need to recruit a substantial number of patients with STAD for the examination of ALKBH1 and the analysis of its correlation with tumor progression." (PMID 38317214, 2024). "Given the critical role of the tumor immune microenvironment (TIME) in tumor progression, metastasis, and immune evasion, we conducted Spearman correlation analysis by TISIDB, which revealed a positive correlation between ALKBH1 expression and the majority of tumor-infiltrating macrophages in STAD." (PMID 38317214, 2024). "Additionally, we also examined the expression levels of m1A regulators in COAD and READ using the online bioinformatics tool GEPIA, which showed that ALKBH1 expression was higher in tumor tissues than that in normal tissues." (PMID 36550779, 2023). "This also suggests that ALKBH1 may be a potential tumor suppressor gene." (PMID 39019857, 2024). "In summary, our study contributes to a deeper comprehension of ALKBH1's role in STAD, particularly from the standpoint of clinical tumor samples, and paves the way for the exploration of novel immunotherapeutic strategies." (PMID 38317214, 2024). "Among the regulatory genes, ALKBH1 and ALKBH3, which are methylation erasers, were upregulated and TRMT10C, TRMT6, TRMT61B, YTHDF2, and YTHDF3 were downregulated in tumor samples in comparison to normal tissues." (PMID 37679761, 2023). "Further analysis indicated that, among overexpressed ALKBH proteins, the greatest difference between tumour and surrounding tissue was observed for ALKBH2 (5-fold), FTO (4-fold), ALKBH1 (3-fold), and 5 (2-fold)." (PMID 31519943, 2019). "Thus, ALKBH1-driven DNA 6 mA demethylation is upregulated under ECM stiffness stimulation, representing a novel epigenetic modification in response to the tumor microenvironment that exacerbates CRC." (PMID 40867005, 2025). "On account of the advance stage which indicates progression, ALKBH1, ALKBH4, ALKBH6, and ALKBH8 may be the potential biomarker for predicting tumor progression." (PMID 35980268, 2022). "ALKBH1 and ALKBH3 were both lowly expressed in tumor and normal samples." (PMID 34777359, 2021). "The eraser ALKBH1 also seems to be an important regulator in GBM, since targeting ALKBH1 in patient-derived GBM models induces cell proliferation inhibition and extends the survival of tumor-bearing mice." (PMID 32244981, 2020). "Similarly, ALKBH1 overexpression promotes metastasis in CRC through modifying METTL3 mRNA m1A levels, resulting in reduced protein translation, increased m6A demethylation of SMAD7 mRNA, and enhanced tumor migration and invasion." (PMID 38317214, 2024).
tumor (continued). "First, the “writer” genes NSUN1-NSUN7, the “eraser” genes TET2 and ALKBH1, and the “reader” genes ALYREF and YBX1 were significantly upregulated or downregulated in tumor tissues, suggesting these genes may be critical in m5C-related occurrence and progression of COAD." (PMID 35281843, 2022). "The expression of ALKBH1 (p = 0.036), ALYREF (p < 0.001), NOP2 (p < 0.001), NSUN2 (p < 0.001), NSUN4 (p < 0.001), NSUN5 (p < 0.001), NSUN6 (p < 0.001), NSUN7 (p = 0.006), and YBX1(p < 0.001) were significantly upregulated in tumor tissues compared with the adjacent mucosa." (PMID 35281843, 2022).
infection (8 papers, 2022 to 2026). The state of being infected such as from the introduction of a foreign agent such as serum, vaccine, antigenic substance or organism. "Early in the infection of human Huh-7 cells, ALKBH1 and its tRNA products 5-formylcytidine (f5C) and 2'-O-methyl-5-formylcytidine (f5Cm) were reduced." (PMID 37986976, 2023). "Surprisingly, the PSI for the ALKBH1 was strongly increased by the WT μ2 harboring the C-term GFP or both P208S mutants, as opposed to the reduction in inclusion of this ASE previously observed during infection." (PMID 35489070, 2022).
ALKBH1 also shares sentences with these, for which no sentence is quoted: atherosclerosis (2 papers); head and neck cancer (2); head and neck squamous cell carcinoma (2); hepatocellular carcinoma (2); urothelial carcinoma (2); childhood cancer (1); colon adenocarcinoma (1); colon cancer (1); digestive system neoplasm (1); intervertebral disc degeneration (1); lactic acidosis (1); liver cancer (1); non-Hodgkin lymphoma (1); ovarian carcinoma (1); prostate carcinoma (1); stomach adenocarcinoma (1); teratozoospermia (1); thyroid cancer (1).